LPAR5 (lysophosphatidic acid receptor 5)
Diseases named in the same sentence as LPAR5 in open-access papers (continued):
Sharing a sentence is not in itself a finding about the gene and the disease.
cancer (continued). "Moreover, increased expression of LPAR5 is significantly associated with IR-induced EMT and confers radioresistance to cancer cells." (PMID 36199069, 2022). "Targeting LPAR5 was proposed to be a good option against cancer development in certain cancers." (PMID 34209775, 2021). "In contrast to LPAR1–3, LPAR4 and LPAR5 negatively affected cancer cell proliferation and motility." (PMID 34209775, 2021). "Nevertheless, contradictory effects of LPAR5 were found in different cancers." (PMID 34209775, 2021). "LPAR5 was considered a negative regulator in cancer cell motility and survival." (PMID 34209775, 2021). "Therefore, LPAR5 knockdown significantly conferred chemo-resistance and enhanced cancer cell survival." (PMID 34209775, 2021). "In addition, ADOR1 and LPAR5 exhibited a hypomethylation state in the cancer group, but APOE showed a hypermethylation state in PTC samples." (PMID 32766727, 2020). "Notably, the Lpar5 mRNA expression levels in several cancer cells correlate with the methylation status of the Lpar5 5′ region." (PMID 31323936, 2019). "The novelty of our study lies in the systematic and comprehensive evaluation of the value of LPAR5 expression in the expression, prognosis, immunity, and other aspects of 33 different types of cancer as well as the exploration of the functions and pathways that LPAR5 might affect or regulate." (PMID 37037831, 2023). "In addition to the cancer cell growth and metastasis, LPAR5 was shown to suppress the function of CD8-positive cytotoxic T cells by inhibiting intracellular Ca2+ mobilization and ERK activation, suggesting LPAR5 might act as a mediator of immune suppression." (PMID 34209775, 2021). "The six upregulated genes (FCGR3A, LPAR5, MATK, MNDA, TMEM144, and CD84) play key immunomodulatory roles in cancer progression and metastasis." (PMID 40340807, 2025). "Lysophosphatidic acid receptor 5 (LPAR5) is considered a prognosis-related gene for pan cancers, and abnormal high-level expression of LPAR5 confers IR-induced epithelial-to-mesenchymal transition (EMT) and radioresistance to cancer cells." (PMID 38473842, 2024). "However, the role of LPAR5 in other cancers remains unclear." (PMID 37037831, 2023). "For anti-cancer CD8+ cells, enrichment was only significantly correlated with high-LPAR5- and LPAR6-expressing tumors (all p < 0.001)." (PMID 37372960, 2023). "Beyond this, the pathway in cancer revealed that most of the genes are relative to WNT pathway (WNT7B, WNT6, WNT10B, FZD6, FZD8, and LPAR5), and among these, WNT7B, WNT10B, FZD6, FZD8, and LPAR5 belonged to the classical WNT pathway." (PMID 34122668, 2021). "The correlation between 60 ICP-related genes and the expression level of LPAR5 was calculated, and the expression level of LPAR5 was found significantly correlated with the expression level of multiple ICP-related genes in various cancer types." (PMID 37037831, 2023). "Epithelial cell (primarily cancer cells) composition was significantly enriched in high-LPAR2 and -LPAR3-expressing tumors in all three cohorts (all p < 0.001) but decreased in high-LPAR1, -LPAR5, and -LPAR6-expressing tumors (all p < 0.05)." (PMID 37372960, 2023). "Overexpression of LPAR5 prompts EMT programing and migration of cancer cells." (PMID 36199069, 2022). "To further clarify the role of LPAR5, we determined its potential action on EMT in cancer cells." (PMID 36199069, 2022). "As an example, inhibition of LPAR5 in distinct cell types, such as CD8+ T cells could help boost its immunosurveillance activity against cancer and impede metastasis." (PMID 32397679, 2020). "Although LPAR5 has been identified as a potential marker of PTC, its immunological aspects have not been studied in PTC or many other cancers." (PMID 37037831, 2023). "Although the relationship between LPAR5 expression and immune cells is not particularly clear, it may be involved in the formation of the TME in different types of cancer." (PMID 37037831, 2023).
LPAR5 also shares sentences with these, for which no sentence is quoted: breast carcinoma (3 papers); endotoxemia (3); ischemic stroke (2); Kidney (2); lung adenocarcinoma (2); adenomyosis (1); adrenocortical carcinoma (1); bladder cancer (1); Bladder Urothelial Carcinoma (1); brain infarction (1); brain injuries (1); cardiovascular disease (1); Cerebral ischemia (1); cervical cancer (1); cervical squamous cell carcinoma (1); childhood asthma (1); cholangiocarcinoma (1); depression (1); diabetes (1); diarrheal disease (1); endocervical adenocarcinoma (1); fibrosarcoma (1); glioblastoma (1); Glucose intolerance (1); Hypertension (1); inflammation (1); injury (1); Insulin resistance (1); invasive breast carcinoma (1); Lung squamous cell carcinoma (1).
A further 13 diseases each share a sentence with LPAR5 in 1 paper.